RSRC1 (arginine and serine rich coiled-coil 1)
Description:
Has a role in alternative splicing and transcription regulation. Involved in both constitutive and alternative pre-mRNA splicing. May have a role in the recognition of the 3' splice site during the second step of splicing.
Synonyms: SRrp53; BM-011; MGC12197; SFRS21; MRT70
Tractability: PROTAC: ubiquitination databases record sites on it; its protein half-life has been measured.
Gene: Protein-coding gene on chromosome 3 (158,105,675 to 158,545,734, forward strand). Ensembl gene ENSG00000174891.
Subcellular location: Nucleus; Nucleus speckle; Cytoplasm
Subcellular location (Human Protein Atlas): Nuclear speckles
Gene Ontology:
Molecular function: protein binding
Biological process: mRNA splicing, via spliceosome; RNA splicing; alternative mRNA splicing, via spliceosome; nucleocytoplasmic transport
Cellular component: cytoplasm; nuclear speck; nucleus
Genetic constraint (gnomAD): Loss-of-function variants: 21 observed, 23.94 expected, observed/expected ratio (o/e) 0.88, 90% interval 0.62 to 1.26. The upper end of that interval is the gene's LOEUF score, 1.26, which puts it in group 5 of 6, group 1 being the genes least tolerant of losing a copy. Missense variants: 267 observed, 262.1 expected, observed/expected ratio (o/e) 1.02, 90% interval 0.92 to 1.13. Synonymous variants: 102 observed, 88.72 expected, observed/expected ratio (o/e) 1.15, 90% interval 0.98 to 1.36.
Gene-disease validity (ClinGen):
ClinGen rates the evidence that RSRC1 causes each of these diseases.
complex neurodevelopmental disorder (autosomal recessive): Definitive. A disorder that involves more than one phenotype associated with the central nervous system, including but not limited to intellectual disability, autism, and seizures (epilepsy).
Homologues: Orthologues: chimpanzee RSRC1 (100% identical), macaque RSRC1 (99% identical), pig RSRC1 (97% identical), rabbit RSRC1 (96% identical), dog RSRC1 (95% identical), guinea pig RSRC1 (94% identical), rat Rsrc1 (93% identical), mouse Rsrc1 (92% identical), tropical clawed frog rsrc1 (63% identical).
Diseases named in the same sentence as RSRC1 in open-access papers:
RSRC1 is named in the same sentence as 15 diseases in open-access papers, as found by Europe PMC text mining. Sharing a sentence is not in itself a finding about the gene and the disease. The quoted sentences say what the papers report.
schizophrenia (4 papers, 2016 to 2025). A major psychotic disorder characterized by abnormalities in the perception or expression of reality. "Variants in RSRC1 are associated with the neurological disease schizophrenia, and RSRC1 is involved in prenatal brain development and cell migration to forebrain structures." (PMID 28545128, 2017). "Recent advances in genetics have revealed RSRC1 mutations are associated with aberrant human brain development: RSRC1 polymorphism is associated with schizophrenia, and patients homozygous for loss‐of‐function RSRC1 mutations exhibit developmental delay and intellectual disability." (PMID 41078088, 2025). "RSRC1 is involved in pre-mRNA splicing as well as a marker of subventricular zone progenitor cells within the foetal and postnatal forebrain, supporting the hypothesis of a developmental aetiology for schizophrenia." (PMID 30142156, 2018).
neuroblastoma (2 papers, 2017 to 2024). Neuroblastoma (NB) is the most common solid, extracranial childhood tumor. "While we did not observe a genotype-expression correlation for RSRC1 or LOC100996447 in neuroblastoma cells, we cannot rule out the possibility that variants at 3q25 influence expression of RSRC1 and/or LOC100996447 genes early in tumorigenesis within developing neural crest cells." (PMID 28545128, 2017).
Abdominal obesity (1 paper, 2021). Excessive fat around the stomach and abdomen. "Seven out of eight identified WC-associated CpGs were also associated with BMI at PFDR < 0.05, and two CpGs cg15103625 in RSRC1 and cg07421368 in ETAA1 were found novel in both WC and BMI associations, indicating common methylation sites influenced by both general and abdominal obesity." (PMID 34670603, 2021).
depression (1 paper, 2024). "The expression of RSRC1, which is also a hub gene in the PPI network of depression-related genes, is significantly up-regulated in depression, demonstrating its critical role of in the pathological process of depression." (PMID 38881665, 2024).
hepatocellular carcinoma (1 paper, 2023). A malignant tumor that arises from hepatocytes. "In the occurrence and development of hepatocellular carcinoma (HCC), the persistent low expression of uc.134, located in the intron region of Rsrc1, may lead to the low survival rate of HCC patients." (PMID 37036543, 2023).
cancer (3 papers, 2017 to 2023). A tumor composed of atypical neoplastic, often pleomorphic cells that invade other tissues. "Since both RSRC1 and MLF1 have been previously implicated in cancer, we investigated the 3q25 locus in more detail." (PMID 28545128, 2017). "Of these 365 cancer positively selected genes, only one gene (RSRC1) also exhibited positive selection whereas 117 genes exhibited negative selection in germline substitutions." (PMID 28938601, 2017). "Taken together, existing studies suggest that RSRC1 may play an important role in both neural stem cell proliferation and cancer development." (PMID 28545128, 2017). "In pan-cancer analysis, SHOX2 expression positive correlated with CDKN2C (R = 0.41), COL6A1 (R = 0.35), COL6A2 (R = 0.37), DCHS1 (R = 0.37), MAPK7 (R = 0.34), PRRX1 (R = 0.37), RAB23 (R = 0.36) and RSRC1 (R = 0.36) via GEPIA2." (PMID 37170390, 2023).
RSRC1 also shares sentences with these, for which no sentence is quoted: neurological disease (2 papers); tumor (2); autism (1); chondropathies (1); developmental delay (1); Intellectual disability (1); metastatic tumours (1); Obesity (1); prostate carcinoma (1).